YJEFN3 (YjeF N-terminal domain containing 3)
Description:
May accelerate cholesterol efflux from endothelial cells to high-density lipoprotein (HDL) and thereby regulates angiogenesis. May orchestrate hematopoietic stem and progenitor cell emergence from the hemogenic endothelium, a type of specialized endothelium manifesting hematopoietic potential. YJEFN3-mediated cholesterol efflux activates endothelial SREBF2, the master transcription factor for cholesterol biosynthesis, which in turn transactivates NOTCH and promotes hematopoietic stem and progenitor cell emergence (By similarity). May play a role in spermiogenesis and oogenesis.
Synonyms: hYjeF_N3-19p13.11; FLJ44968
Tractability: No criterion of Open Targets' tractability assessment is met for any kind of drug.
Gene: Protein-coding gene on chromosome 19 (19,528,861 to 19,537,584, forward strand). Ensembl gene ENSG00000250067.
Subcellular location (Human Protein Atlas): Mitochondria
Gene Ontology:
Molecular function: protein binding; NAD(P)HX epimerase activity
Biological process: hematopoietic stem cell proliferation; membrane raft distribution; negative regulation of angiogenesis; regulation of cholesterol efflux; regulation of Notch signaling pathway; sprouting angiogenesis
Cellular component: mitochondrion
Genetic constraint (gnomAD): Loss-of-function variants: 29 observed, 27.33 expected, observed/expected ratio (o/e) 1.06, 90% interval 0.79 to 1.45. The synonymous counts are far from expectation, so gnomAD's model fits this gene poorly and the ratio says little. Missense variants: 442 observed, 383.17 expected, observed/expected ratio (o/e) 1.15, 90% interval 1.07 to 1.25. Synonymous variants: 227 observed, 181.97 expected, observed/expected ratio (o/e) 1.25, 90% interval 1.12 to 1.39.
Homologues: Orthologues: chimpanzee YJEFN3 (100% identical), macaque YJEFN3 (97% identical), pig YJEFN3 (77% identical), dog YJEFN3 (72% identical), guinea pig YJEFN3 (71% identical), mouse Yjefn3 (68% identical), tropical clawed frog yjefn3 (51% identical), zebrafish yjefn3 (49% identical), Drosophila melanogaster Naxe (31% identical), Caenorhabditis elegans Y18D10A.3 (29% identical). Paralogues in human: NAXE (40% identical).
Diseases named in the same sentence as YJEFN3 in open-access papers:
YJEFN3 is named in the same sentence as 8 diseases in open-access papers, as found by Europe PMC text mining. Sharing a sentence is not in itself a finding about the gene and the disease. The quoted sentences say what the papers report.
cervical cancer (1 paper, 2021). A primary or metastatic malignant neoplasm involving the cervix. "The remaining 10 genes (i.e., YJEFN3, SPATA5L1, C5orf55, PPM1A, IMMP1L, ZNF330, PPIP5K2, ESCO2, FICD, and ZNF225) are not directly reported to be related to the survival risk of cervical cancer in previous literature." (PMID 34149809, 2021).
colorectal cancer (1 paper, 2025). A primary or metastatic malignant neoplasm that affects the colon or rectum. "Among these, genes with positive coefficients (ABHD4, ABHD8, YJEFN3, CRYAB, and HSPA1A) were found to be risk factors, suggesting that their increased expression is associated with worse prognoses in colorectal cancer patients." (PMID 41293172, 2025). "In this study, we constructed a prognostic nomogram incorporating ABHD4, YJEFN3, and key clinical parameters to improve individualized survival prediction in colorectal cancer (CRC)." (PMID 41293172, 2025). "To further elucidate the functional relevance of ABHD4 and YJEFN3 as independent prognostic biomarkers, we explored their expression patterns in different cellular compartments of the colorectal cancer tumor microenvironment using the TISCH2 single-cell transcriptomic database." (PMID 41293172, 2025).
fibroma (1 paper, 2021). A non-metastasizing neoplasm arising from the fibrous tissue. "Specifically, for example, YJEFN3 is a member of the human YJEFN domain-containing protein family strongly expressing in Leydig cell tumors and in the fibromas and participates in cholesterol processing and steroid hormone metabolism." (PMID 34149809, 2021).
Parkinson disease (1 paper, 2021). A progressive degenerative disorder of the central nervous system characterized by loss of dopamine producing neurons in the substantia nigra and the presence of Lewy bodies in the substantia nigra and locus coeruleus. "For example, genetic and methylomic variation in YJEFN3 has shown associations with schizophrenia and common and rare genetic variants in GCH1 are associated with Parkinson’s disease." (PMID 33684137, 2021).
prostate adenocarcinoma (1 paper, 2025). "YJEFN3 (YjeF N-terminal domain-containing protein 3) has been identified as a tumor-associated antigen in prostate adenocarcinoma (PRAD), where its overexpression and mutations are linked to poor prognosis and altered immune cell infiltration." (PMID 41293172, 2025).
tumor (2 papers, 2021 to 2025). "Moreover, transwell and wound healing assays revealed that the knockdown of either gene significantly impaired the migratory and invasive capabilities of CRC cells, suggesting that both ABHD4 and YJEFN3 are positively associated with tumor cell aggressiveness." (PMID 41293172, 2025). "In contrast, YJEFN3 expression was predominantly enriched in malignant epithelial (tumor) cells, whereas its expression was markedly lower in immune cells." (PMID 41293172, 2025). "We identified eight overexpressed and mutated tumor antigens with poor prognostic value of PRAD, including KLHL17, CPT1B, IQGAP3, LIME1, YJEFN3, KIAA1529, MSH5 and CELSR3." (PMID 34872584, 2021). "In addition, silencing ABHD4 and YJEFN3 suppressed CRC cell proliferation and motility, validating their role in tumor progression and suggesting their potential as therapeutic targets with clinical relevance." (PMID 41293172, 2025).
YJEFN3 also shares sentences with these, for which no sentence is quoted: Leydig cell tumor (1 paper); schizophrenia (1).